CTLA4 (cytotoxic T-lymphocyte associated protein 4)
Diseases named in the same sentence as CTLA4 in open-access papers (continued):
Sharing a sentence is not in itself a finding about the gene and the disease.
injury (3 papers, 2011 to 2024). Damage inflicted on the body as the direct or indirect result of an external force, with or without disruption of structural continuity. "In trauma patients, CTLA-4 and PD-1 expressions were elevated in anergic T cells." (PMID 21418617, 2011).
intestinal inflammation (3 papers, 2020 to 2025). "Two patients with LRBA and CTLA4 deficiency were put on abatacept then infliximab to manage rheumatological and intestinal inflammation." (PMID 40703516, 2025). "We propose that this population of CTLA-4-positive ILC may serve as an important target for the treatment of idiopathic and iatrogenic intestinal inflammation." (PMID 39496592, 2024).
latent infections (3 papers, 2016 to 2022). "In line with our MIBI-TOF analysis, differential expression of genes associated with regulatory myeloid cells (e.g., PD-L1, PD-L2, CD11b, CD11c and CD163) or T cell immune checkpoint (e.g., PD-1 and CTLA4) delineated active from latent infections." (PMID 35058616, 2022). "Therefore, PD-1 and CTLA-4 may play a homeostatic role in controlling the excessive inflammation that occurs in TB disease, but overexpression on T-cells during latent infection could inhibit protective T-cell responses leading to disease progression." (PMID 27367521, 2016).
mammary adenocarcinoma (3 papers, 2021 to 2025). "Thus, here we set out to analyze the in vitro effects of inhibiting CTLA-4 and PD-1 on interactions between co-cultured lymphocytes and two selected breast adenocarcinoma cell lines." (PMID 34440813, 2021).
myeloid malignancies (3 papers, 2024 to 2025). "The ICIs investigated in myeloid malignancies include those targeting T-cell checkpoints PD-1, PD-L1, and CTLA-4, as well as the macrophage checkpoint CD47." (PMID 39199554, 2024). "Upregulation of immune inhibitory checkpoints PD1, CTLA4, and CD47 has been consistently documented in myeloid neoplasms driving many prior clinical trials of antibodies aimed at blocking these proteins in patients with MDS and AML." (PMID 40111422, 2025).
Papillary thyroid cancer (3 papers, 2021 to 2024). "Papillary thyroid cancer infiltrating T cells consisted of CD3+ cytotoxic T cell, CD8+ cytotoxic cell, and CTLA4+ and CD4+ Treg cells." (PMID 34805166, 2021).
paracoccidioidomycosis (3 papers, 2020 to 2024). A systemic fungal infection caused by Paracoccidioides brasiliensis that is most often seen in immunocompromised patients. "Antibody-mediated blockade of CTLA-4 enhanced IFN-γ responses of ex-vivo PBMCs from patients with paracoccidioidomycosis." (PMID 36389687, 2022). "T-cells from patients with active paracoccidioidomycosis showed increased expression of CTLA-4 and decreased proliferative capacity after stimulation with the strong T-cell activator phytohemagglutinin." (PMID 36389687, 2022). "As the immunosuppression of severe paracoccidioidomycosis (PCM), a chronic granulomatous fungal disease, was shown to be associated with the expression of coinhibitory molecules, we hypothesized that the inhibition of CTLA-4 and PD-1 could have a beneficial effect on pulmonary PCM." (PMID 38500881, 2024). "The PD1 and CTLA-4 pathways have roles to play in antifungal defences, as demonstrated in vitro in a murine model of Histoplasma capsulatum infection (PD1) and in blood from patients with paracoccidioidomycosis (CTLA-4)." (PMID 33072081, 2020).
pleural mesothelioma (3 papers, 2024 to 2025). A neoplasm that arises from the mesothelial cells of the pleura. "Co-targeting of immune checkpoint inhibitors (ICI) CTLA-4 and PD-1 has recently become the new first-line standard of care therapy of pleural mesothelioma (PM) patients, with a significant improvement of overall survival (OS) over conventional chemotherapy." (PMID 39966970, 2025). "al showed only modest responses to combination CPI therapy with nivolumab (anti-PD1) and ipilimumab (anti-CTLA4) as a first line treatment for pleural mesothelioma, although long term responders were established." (PMID 38642130, 2024).
pneumococcal pneumonia (3 papers, 2018 to 2019). A febrile disease caused by STREPTOCOCCUS PNEUMONIAE. "Similarly, interference with CTLA-4 function improved survival in bacterial and fungal sepsis as well as in pneumococcal pneumonia." (PMID 29415028, 2018).
psoriasis vulgaris (3 papers, 2009 to 2023). Plaque psoriasis is the most common presentation of psoriasis. "We aimed to determine whether CTLA-4 gene polymorphisms are associated with development and/or clinical features of psoriasis vulgaris (Pv)." (PMID 29850619, 2018). "With this hypothesis, our goal was (i) to investigate whether the CTLA-4 gene polymorphisms are related to the development of Pv (psoriasis vulgaris) and (ii) to detect whether the CTLA-4 gene polymorphisms have an impact on the clinical features of P. vulgaris such as onset age and severity." (PMID 29850619, 2018). "Although CTLA-4-Ig was studied in a phase 1 clinical trial for patients with psoriasis vulgaris (NCT00306878, NCT0027722); the study was discontinued in 2011, and no results have been reported." (PMID 37818377, 2023). "Recently, the efficacy of CTLA4-Ig has been investigated in human clinical trials to prevent transplant rejection, and in the treatment of RA and psoriasis vulgaris." (PMID 19333372, 2009).
pulmonary TB (3 papers, 2009 to 2021). "Our findings do not provide evidence for a role of the +6230 polymorphism of human CTLA4 in protection against pulmonary TB." (PMID 19609446, 2009). "Thus, the CTLA4 +6230 polymorphism was found to influence pulmonary TB only after Mycobacterium tuberculosis had overcome innate and adaptive host defence mechanisms." (PMID 19609446, 2009). "Interestingly, our study reveals an important role for both PD-1 and CTLA-4 signaling in the down modulation of Tfh cell expansion in pulmonary TB since blockade of either of these pathways significantly restored the TB - antigen induced expansion of Tfh cell subsets in PTB individuals." (PMID 25343703, 2014). "Accordingly, pulmonary TB appears not to belong to those infections which may contribute to explain the high prevalence of CTLA4 +6230G in human populations." (PMID 19609446, 2009).
relapsing-remitting MS (3 papers, 2021 to 2025). "Tregs acquire a phenotype and expression profile resembling Th1 cells, thereby contributing to disease progression: Lower expression levels of Foxp3, TGF, CTLA-4 and CD39 were accompanied by an increase in IFN secretion in relapsing-remitting MS (RRMS) patients." (PMID 34691057, 2021).
respiratory infections (3 papers, 2021 to 2024). "CTLA4 deficiency is a rare disorder profoundly disrupting immune system regulation, leading to conditions such as intestinal disease, respiratory infections, autoimmune issues, and enlarged lymph nodes, liver, and spleen." (PMID 38644452, 2024). "The transcriptional changes (including AP4B1-AS1 and CTLA4) we identified in the lung may help explain the reported association between respiratory infections and risk of islet autoantibody seroconversion reported in young children." (PMID 34521982, 2021).
sarcopenia (3 papers, 2018 to 2022). Progressive decline in muscle mass due to aging which results in decreased functional capacity of muscles. "Body composition and sarcopenia seem to be prognostic of enhanced chemotherapy and targeted therapy toxicity, and more recently with immune checkpoint inhibitors such as anti-CTLA-4 (ipilimumab)." (PMID 30286724, 2018).
scleritis (3 papers, 2020 to 2021). Inflammation of the sclera. "A significantly increased frequency of the GG genotype and G allele of rs3087243 in CTLA4 has been reported in scleritis." (PMID 33287909, 2020).
severe combined immunodeficiency (3 papers, 2021 to 2025). Severe combined immunodeficiency (SCID) comprises a group of rare monogenic primary immunodeficiency disorders characterized by a lack of functional peripheral T lymphocytes resulting in early-onset severe respiratory infections and failure to thrive. "The most common diagnoses in this group included severe combined immunodeficiency (T-B+ SCID) affecting 17 patients (30.9%), CTLA-4 deficiency (12; 21.8%), and CD40L deficiency (9; 16.4%)." (PMID 41030454, 2025).
Sézary syndrome (3 papers, 2015 to 2022). "CTLA-4 expression is upregulated in patients with peripheral T-cell lymphoma, mycosis fungoides, and Sézary syndrome, but not seen in B-cell lymphoma." (PMID 28482851, 2017).
silicosis (3 papers, 2010 to 2025). Silicosis is a respiratory disease caused by breathing in (inhaling) silica dust. "At the early stage of silicosis, T regulatory cells mainly inhibited inflammation by CTLA-4 molecules." (PMID 25299237, 2014). "These suggested that during the inflammatory stage of silicosis, Treg cells suppressed the inflammation and Th1 immune response directly by expressing CTLA-4 molecule." (PMID 21072213, 2010). "In addition, Lilr4a, Lilr4b, and Tnfsf18 were significantly up-regulated in the early and middle stages of silicosis, while Pdcd1, Ctla4, and Tigit were significantly up-regulated in the middle and late stages of silicosis." (PMID 39498466, 2025). "At the early stage of silicosis, Treg cells mainly inhibited the inflammation by CTLA-4 molecule." (PMID 21072213, 2010).
thymic carcinoma (3 papers, 2018 to 2022). Thymic carcinoma (TC) is a type of thymic epithelial neoplasm characterized by a high malignant potential. "Moreover, although the number of thymoma type C samples was limited to be included in the statistical analysis, the immunohistochemistry was performed and showed a strong CTLA-4 staining in these specimens." (PMID 29682176, 2018). "Given the small number of thymoma type C samples, the expression of CTLA-4 mRNA was not evaluated in these specimens." (PMID 29682176, 2018).
uterine corpus endometrial carcinoma (3 papers, 2020 to 2023). A endometrial carcinoma (disease) that involves the body of uterus. "Regarding uterine corpus endometrial carcinoma (UCEC), we observed a young-bias pattern concerning immune checkpoints (CTLA-4, ICOS, and so on) and CYT (p=0.013) and validated it in an independent dataset." (PMID 33936087, 2021).
abscess (2 papers, 2017 to 2024). An inflammatory process characterized by the accumulation of pus within a newly formed tissue cavity which is the result of a bacterial, fungal, or parasitic infection or the presence of a foreign body. "It was proved that T cell activation by APCs through the CD28-B7 interaction is crucial for abscess formation as well as that the signalling through CTLA-4 (which is a cellular antagonist of CD28)-B7 inhibits abscess formation." (PMID 38397099, 2024). "This is not quite unique because previous studies have demonstrated that blockade of T-cell activation by CTLA4 Ig prevents abscess formation in mice infected with different bacterial pathogens including S. aureus." (PMID 28264025, 2017).
Acute hepatitis (2 papers, 2016 to 2019). Acute hepatic injury resulting from inflammation typically accompanied by increased serum alanine transaminase activity. "Therefore, this study determined the effect of blocking the cluster of differentiation 28/ cytotoxic T-lymphocyte-associated antigen 4/B7 (CD28/CTLA-4/B7) costimulatory pathway by SC injection of abatacept with respect to the development of acute hepatitis in BALB/c mice." (PMID 31064410, 2019). "CTLA-4 revealed its viral-protective effect as inhibitory molecules that suppressed cytotoxic T-cells and thereby prevented the destruction of virus-infected hepatocytes in symptomatic acute hepatitis." (PMID 27617959, 2016).
acute leukemia (2 papers, 2016 to 2020). A clonal (malignant) hematopoietic disorder with an acute onset, affecting the bone marrow and the peripheral blood. "In this study, we focused on four CTLA-4 polymorphisms, and analyzed the impact of donor genotypes and haplotypes on the conditions of 152 acute leukemia patients (ALL 83) after related HLA-haplotype- mismatched transplantation." (PMID 27118383, 2016). "In the present study, we focused on these four CTLA-4 polymorphisms and analyzed the impact of donor genotypes and haplotypes in 152 acute leukemia (ALL 83) patients on the outcomes after related HLA-haplotype-mismatched transplantation." (PMID 27118383, 2016). "First results with PD-1 or/and CTLA-4 blockade indicate best responses in relapsed HD, but also other hematological malignancies, such as acute leukemia and NHL, show adequate responses to CI after allo-HCT." (PMID 32455836, 2020).
acute liver failure (2 papers, 2020 to 2022). Rapid deterioration of liver function causing encephalopathy and coagulopathy. "Patients with acute liver failure demonstrate reduced proliferation capacity and increased expression of CTLA-4 on circulating CD4 T cells, and ex vivo treatment with anti-CTLA-4 antibody restores the proliferative response." (PMID 33613563, 2020).
Ageusia (2 papers, 2022 to 2023). A rare condition that is characterized by a complete loss of taste function of the tongue. "We also observed a lower Treg CTLA-4+ frequency in Pool CoV-2-stimulated PBMC from Mild Recovered volunteers who had experienced fatigue, anosmia, and ageusia than in those who had not developed these symptoms." (PMID 36969257, 2023).
AIDS (2 papers, 2020 to 2021). A syndrome resulting from the acquired deficiency of cellular immunity caused by the human immunodeficiency virus (HIV). "Polymorphisms in CTLA-4 gene were also associated with disease susceptibility to many AIDs like SLE, RA, MS, T1D, and so on." (PMID 33692958, 2021).
alcoholic liver diseases (2 papers, 2009 to 2012). A disorder caused by damage to the liver parenchyma due to alcohol consumption. "Of note, CTLA-4 expression was low in CD8 T cells from liver explants of two HCV-seronegative patients with nonalcoholic steatohepatitis and alcoholic liver disease." (PMID 19247441, 2009).
allergic rhinitis (2 papers, 2009 to 2011). Inflammation of the nasal mucous membranes caused by an IgE-mediated response to external allergens. "In allergic rhinitis, an allergen-induced Treg cell deficiency is seen, as well as an ICOS-, CD28- and CTLA-4-dependent Th2 activation." (PMID 21356099, 2011).
ankylosing spondylitis (2 papers, 2023 to 2024). An autoimmune chronic inflammatory disorder characterized by inflammation in the vertebral joints of the spine and sacroiliac joints. "The study found that the HLA-B27 antigen and variations in the CTLA4 3’UTR region played an essential role in ankylosing spondylitis susceptibility in a west Algerian population." (PMID 39063056, 2024). "Markers such as PD-1 and CTLA-4 have been extensively studied and facilitate the concept of an impaired negative immune regulation in ankylosing spondylitis." (PMID 36883249, 2023).
Anosmia (2 papers, 2022 to 2023). An inability to perceive odors. "Pool CoV-2-stimulated PBMC presented fewer Tregs expressing CTLA-4 in those who had developed anosmia when compared with that of the unstimulated samples." (PMID 36969257, 2023).
aortic aneurysm (2 papers, 2019 to 2022). A ruptured aneurysm located in the wall of the proximal portion of the descending aorta proceeding from the arch of the aorta. "Histological analysis of the aortic aneurysm tissues revealed that angiotensin II-infused CTLA-4-Tg/Apoe−/− mice had more preserved elastin content compared with control mice." (PMID 31147569, 2019). "FOXP3+ Treg cells were abundant in aortic aneurysms, especially in AAA groups and displayed high expression of exhausted genes CTLA4, TIGIT, TNFRSF14, ICOS, and CD28." (PMID 36703732, 2022).
aplastic anemia (2 papers, 2020 to 2024). Anemia resulting from bone marrow failure (aplastic or hypoplastic bone marrow). "In this report, we present a novel CTLA4 variant manifesting as aplastic anemia and provide functional testing that confirms this novel variant is deleterious to CTLA-4 expression resulting in severely reduced transendocytosis." (PMID 39220156, 2024). "Given the patient's clinical phenotype, known risk for immune dysregulation with CTLA4 variants, and without other identifiable etiologies for the aplastic anemia, a research-based functional assay was pursued." (PMID 39220156, 2024).
autoimmune encephalitis (2 papers, 2020 to 2021). Inflammation of the brain secondary to an immune response triggered by the body itself. "Although CNS‐irAEs are possible with all ICPIs, including CTLA‐4, PD‐1, and PD‐L1 inhibitors, this study analyzed a PD‐L1 inhibitor because autoimmune encephalitis cases by the other drugs were rare in our institution." (PMID 33031633, 2020).
autoimmune uveitis (2 papers, 2022 to 2025). An autoimmune form of uveitis (disease). "This also promoted reduction in SE-related Th1 gene expression (e.g. Ifng, Tnf, Fasl, IL18 and Ctla4), which caused disease remission in autoimmune uveitis mice." (PMID 35514959, 2022). "Instead, immune checkpoint modulators that dampen immune activation—such as CTLA-4-Ig (abatacept)—have demonstrated efficacy in experimental autoimmune uveitis models by expanding Tregs and reducing pro-inflammatory Th17 cytokines, thus curbing inflammation." (PMID 41268982, 2025). "CTLA-4 represents a significant immune checkpoint in ocular conditions, especially those characterized by immune dysregulation, such as autoimmune uveitis." (PMID 41268982, 2025).
bronchiolitis obliterans (2 papers, 2015 to 2021). "An upregulation of cytotoxic T-lymphocyte-associated protein 4 (CTLA-4 = CD152) was detected on CD4+CD28− T cells from healthy subjects and patients with bronchiolitis obliterans syndrome." (PMID 25834833, 2015). "The molecules 4-1BB and CTLA-4 are responsible for the production of cytotoxic T cells before or during graft rejection and OX40 and CD40L are important for proliferation and cytokine production of CD4+CD28− T cells in bronchiolitis obliterans syndrome." (PMID 25834833, 2015).
cervical (2 papers, 2021 to 2025). "Single-nucleotide variants (SNVs) in the CTLA4 gene can alter the gene expression and immune response against HPV, influencing cervical malignancy progression." (PMID 40284896, 2025). "What stood out in the tables was the patients afflicted with the cervical disease showed positive correlation significantly, such as famous immune checkpoint genes (CTLA4, TIGIT, HAVCR2, LAG3, etc.)and costimulatory genes like ICOS, CD80, CD40, and so forth." (PMID 33694292, 2021).
Cholecystitis (2 papers, 2019 to 2025). The presence of inflammatory changes in the gallbladder. "Anti–CTLA-4 monotherapy was associated with a higher risk of cholecystitis (P = 0.006)." (PMID 31053161, 2019). "We found that cholecystitis occurred significantly more frequently among anti–CTLA-4 recipients than among patients receiving other ICIs (P = 0.006), and this trend is similar to that among other irAEs." (PMID 31053161, 2019). "Patients who received a combination of anti–CTLA-4 and anti–PD-1/L1 had more complications of cholecystitis than did patients who received either agent alone (P = 0.03)." (PMID 31053161, 2019).
clear cell adenocarcinoma (2 papers, 2019 to 2024). A malignant neoplasm composed of glandular epithelial clear cells. "In another preliminary study on metastatic renal cell carcinoma, 18 patients with clear cell carcinoma and 11 patients with non-clear cell carcinoma underwent treatment with anti-CTLA-4 (Tremelimumab) monotherapy (n=14) or a combination of cryoablation and anti-CTLA-4 (n=15)." (PMID 38384806, 2024). "The results showed a significant increase in tumor-infiltrating T lymphocytes in patients with clear cell carcinoma in the combination therapy group compared to anti-CTLA-4 monotherapy, while no similar phenomenon was observed in patients with non-clear cell carcinoma." (PMID 38384806, 2024).